PRPF8 (pre-mRNA processing factor 8)
Description:
Plays a role in pre-mRNA splicing as core component of precatalytic, catalytic and postcatalytic spliceosomal complexes, both of the predominant U2-type spliceosome and the minor U12-type spliceosome. Functions as a scaffold that mediates the ordered assembly of spliceosomal proteins and snRNAs. Required for the assembly of the U4/U6-U5 tri-snRNP complex, a building block of the spliceosome. Functions as a scaffold that positions spliceosomal U2, U5 and U6 snRNAs at splice sites on pre-mRNA substrates, so that splicing can occur. Interacts with both the 5' and the 3' splice site.
Synonyms: PRPC8; Prp8; hPrp8; SNRNP220; RP13
Tractability: Small molecule: a structure with a bound ligand is known; it has a high-quality binding pocket. PROTAC: ubiquitination databases record sites on it; its protein half-life has been measured.
Gene: Protein-coding gene on chromosome 17 (1,650,624 to 1,684,876, reverse strand). Ensembl gene ENSG00000174231.
Subcellular location: Nucleus; Nucleus speckle
Subcellular location (Human Protein Atlas): Nuclear speckles; Nucleoplasm
Pathways (Reactome):
Metabolism of RNA: mRNA Splicing - Major Pathway; mRNA Splicing - Minor Pathway
Disease: Dengue Virus-Host Interactions
Gene Ontology:
Molecular function: K63-linked polyubiquitin modification-dependent protein binding; protein binding; RNA binding; metal-dependent deubiquitinase activity; peptidase activity; second spliceosomal transesterification activity; U5 snRNA binding; U6 snRNA binding
Biological process: mRNA splicing, via spliceosome; spliceosomal tri-snRNP complex assembly; mRNA cis splicing, via spliceosome; mRNA processing; negative regulation of mRNA splicing, via spliceosome; RNA splicing; RNA splicing, via transesterification reactions; spliceosomal snRNP assembly; spliceosome conformational change to release U4 (or U4atac) and U1 (or U11); cellular response to lipopolysaccharide; cellular response to tumor necrosis factor
Cellular component: catalytic step 2 spliceosome; membrane; nuclear speck; nucleoplasm; nucleus; post-mRNA release spliceosomal complex; post-spliceosomal complex; precatalytic spliceosome; spliceosomal complex; U12-type catalytic step 2 spliceosome; U12-type precatalytic spliceosome; U2-type catalytic step 1 spliceosome; U2-type catalytic step 2 spliceosome; U2-type precatalytic spliceosome; U4/U6 x U5 tri-snRNP complex; U4atac/U6atac x U5 tri-snRNP complex; U5 snRNP; small nuclear ribonucleoprotein complex
Genetic constraint (gnomAD): Loss-of-function variants: 64 observed, 302.58 expected, observed/expected ratio (o/e) 0.21, 90% interval 0.17 to 0.26. The upper end of that interval is the gene's LOEUF score, 0.26, which puts it in group 1 of 6, group 1 being the genes least tolerant of losing a copy. Missense variants: 1,426 observed, 3,176.3 expected, observed/expected ratio (o/e) 0.45, 90% interval 0.43 to 0.47. Synonymous variants: 1,325 observed, 1,188.7 expected, observed/expected ratio (o/e) 1.11, 90% interval 1.07 to 1.17.
Homologues: Orthologues: chimpanzee PRPF8 (100% identical), dog PRPF8 (100% identical), guinea pig PRPF8 (100% identical), pig PRPF8 (100% identical), rabbit PRPF8 (100% identical), mouse Prpf8 (99% identical), rat Prpf8 (99% identical), macaque PRPF8 (99% identical), tropical clawed frog prpf8 (99% identical), zebrafish prpf8 (98% identical), Drosophila melanogaster Prp8 (92% identical), Caenorhabditis elegans prp-8 (87% identical).
Diseases named in the same sentence as PRPF8 in open-access papers:
PRPF8 is named in the same sentence as 71 diseases in open-access papers, as found by Europe PMC text mining. Sharing a sentence is not in itself a finding about the gene and the disease. The quoted sentences say what the papers report.
retinitis pigmentosa (23 papers, 2011 to 2025). Retinitis pigmentosa (RP) is an inherited retinal dystrophy leading to progressive loss of the photoreceptors and retinal pigment epithelium and resulting in blindness usually after several decades. "As the second and third PE targets, we chose PRPF3 and PRPF8 associated with autosomal dominant (ad) forms of retinitis pigmentosa (RP)." (PMID 39795970, 2024). "A subset of patients with retinitis pigmentosa (RP) carry mutations in several spliceosomal components including the PRPF8 protein." (PMID 37019475, 2023). "Retinitis pigmentosa is a genetic disorder of the eyes characterized by a loss of vision and is sometimes caused by mutations in specific spliceosomal proteins, such as PRPF8 and SNRNP200." (PMID 36560714, 2022). "Fibroblasts from a patient with splicing factor retinitis pigmentosa caused by a missense mutation in the PRPF8 splicing factor were used to produce three diseased and three CRISPR/Cas9-corrected induced pluripotent stem cell (iPSC) clones." (PMID 30572641, 2018). "This would be in agreement with the observation that mutation in other spliceosome components besides PRPF8 can cause retinitis pigmentosa in humans." (PMID 30333215, 2018). "Our results provide evidence that a non-synonymous mutation in the splicing factor PRPF8 that leads to retinitis pigmentosa affects the inclusion of approximately 20% of the exons in genes expressed in whole blood samples." (PMID 24969741, 2014). "Expression of pathogenic PRPF8 variants responsible for retinitis pigmentosa induced apoptosis." (PMID 36560714, 2022). "Finally, the question remains as to how a point mutation in a ubiquitously expressed splicing factor, such as PRPF8, can cause retinitis pigmentosa." (PMID 30572641, 2018). "PRPF8 deficiency is linked to human diseases like retinitis pigmentosa or myeloid neoplasia, but its genome-wide effects on constitutive and alternative splicing remain unclear." (PMID 26392272, 2015). "Overall, our results support the hypothesis that a mutation in the splicing factor PRPF8 that leads to retinitis pigmentosa, has a widespread impact on mRNA splicing across the transcriptome." (PMID 24969741, 2014). "Variants in TXNL4A and EFTUD2 manifest in craniofacial malformations while variants in PRPF8 and SNRNP200 manifest in retinitis pigmentosa." (PMID 40264708, 2025). "Among these, the prognosis for mutant PRPF8 was better than that for wild-type PRPF8 in retinitis pigmentosa." (PMID 40136404, 2025). "Mutations in PRPF8 and SNRNP200 are found in patients with retinitis pigmentosa (RP), a human hereditary disease characterized by the loss of photoreceptors and degenerative changes in the retinal pigment epithelium (RPE)." (PMID 40045025, 2025). "Mutations in genes encoding the splicing factors PRPF3, PRPF8, PRPF31, RP9, and SNRNP200 can cause non-syndromic retinitis pigmentosa, a severe form of inherited blindness leading to rod photoreceptor degeneration." (PMID 26985665, 2016). "Retinitis pigmentosa is also caused by mutations in components of the splicing machinery, such as U4/U6 small nuclear ribonucleoprotein Prp3 (PRPF3), PRPF8, and PRPF31, suggesting a considerable role of RNA biology in this disease." (PMID 26520658, 2015). "Two previous studies of the effects of mutations in three splicing factors (PRPF3, PRPF8 and PRPF31) linked to retinitis pigmentosa on mRNA splicing in lymphoblast cells reported evidence of retained introns." (PMID 24969741, 2014). "Mutations in six spliceosomal proteins, PRPF3, PRPF4, PRPF6, PRPF8, PRPF31 and SNRNP200, cause retinitis pigmentosa (RP), a disease characterized by progressive photoreceptor degeneration." (PMID 25383878, 2014). "Moreover, PRPF8 has been reported to induce mitophagy in response to hypoxia in retinitis pigmentosa." (PMID 39273537, 2024). "Neither wild-type nor mutant PRPF8 (as observed in retinitis pigmentosa) affected cell proliferation." (PMID 40136404, 2025).
autosomal dominant retinitis pigmentosa (11 papers, 2013 to 2023). Autosomal dominant retinitis pigmentosa (RP) is an autosomally dominant inherited retinal dystrophy leading to progressive loss of the photoreceptors and retinal pigment epithelium and resulting in blindness usually after several decades. "Mutations in PRPF8 contribute to pathogenesis of autosomal dominant retinitis pigmentosa, a hereditary degenerative eye disease with a progressive loss of photoreceptor cells." (PMID 35585060, 2022). "It is reported that PRPF8 mutation caused aberrant splicing in some human diseases, such as myeloid malignancies and autosomal-dominant retinitis pigmentosa." (PMID 34434935, 2021). "Mutations in PRPF8 have been associated with autosomal dominant retinitis pigmentosa (adRP) with rod-dominated defects." (PMID 30689892, 2019). "Mutations in human PRPF8 that affects spliceosome assembly and function are found in autosomal dominant retinitis pigmentosa (RP) (OMIM 600059), characterized by a progressive degeneration of the rod and cone photoreceptors in the retina." (PMID 28707069, 2018). "Previously, PRPF8 mutations have been associated with autosomal dominant retinitis pigmentosa (RP)." (PMID 28707069, 2018). "Finally, the only DUB-related gene that has been directly involved in human inherited retinal degeneration and causative of autosomal dominant Retinitis Pigmentosa is PRPF8, the JAMM-family member with the highest level of expression in the retina." (PMID 26934049, 2016). "Pre-mRNA processing factors (PRPF6, PRPF8, and PRPF31) mutated in autosomal dominant retinitis pigmentosa and were identified as regulators during ciliogenesis." (PMID 36759599, 2023). "Remarkably, whereas expression of wild-type PRPF8 protein can rescue the hypoxic mitophagy defect observed in PRPF8 knockdown cells, expression of PRPF8R2310K, an autosomal dominant retinitis-pigmentosa associated mutant, is ineffective in doing so22." (PMID 35585060, 2022). "PRPF8 (OMIM: 607300) encodes for precursor mRNA-processing factor 8, a spliceosome component, a gene known to cause autosomal dominant retinitis pigmentosa (ADRP, RP13 MIM: 600059)." (PMID 33712029, 2021). "At least six different proteins of the spliceosome, including PRPF3, PRPF4, PRPF6, PRPF8, PRPF31, and SNRNP200, are mutated in autosomal dominant retinitis pigmentosa (adRP)." (PMID 30967900, 2019).
myeloid malignancies (9 papers, 2017 to 2025). "Somatic mutations in PRPF8 have been associated with myeloid neoplasms, and overexpression of PRPF8 increases the aggressiveness of hepatocellular carcinoma." (PMID 41315142, 2025). "Studies have shown that functional loss caused by mutations and del(17p) in PRPF8 is closely associated with poor prognosis in myeloid tumor patients." (PMID 40136404, 2025). "In addition to the role of PRPF8 in RP, recurrent somatic mutations and hemizygous deletions have been identified in PRPF8 in myeloid neoplasms including myelodysplastic syndrome (MDS)." (PMID 33584830, 2021). "However, somatic mutations in PRPF8 have now been linked to myeloid neoplasms, while altered expression levels of several other U5 snRNP proteins (PRPF6, EFTUD2, SNRNP40, and DDX23) have been associated with human cancer." (PMID 33584830, 2021). "For example, since PRPF8 mutations have been identified in myeloid malignancies, therapeutics that target HR-deficiency may be worth considering for this patient population." (PMID 29212152, 2017). "Precisely how and why these PRPF8 mutations impact the overall function of PRPF8 protein resulting in neomorphic splicing activity and leading to the malignant phenotype of aggressive myeloid malignancies with increased RS is not yet understood (Ru°žičková and Staněk, 2017)." (PMID 33584830, 2021). "Based on studies of the yeast Prp8 protein, PRPF8 protein appears to be involved in spliceosome assembly, however a clear function in myeloid malignancies has not yet been demonstrated." (PMID 31766606, 2019). "Furthermore, some studies indicate that PRPF8 splicing dysregulation is related to increased myeloid cells, although no reports have confirmed its specific role in myeloid malignancies." (PMID 40136404, 2025).
retinal degeneration (8 papers, 2016 to 2025). Degeneration of the retina. "This suggests that changes in the expression and splicing of specific genes are the main driver of retinal degeneration in PRPF8-linked RP." (PMID 40045025, 2025). "This study shows that Prpf8 mutations associated with human retinal degeneration in mice alter circRNA expression in cerebellar granule cells and induce their apoptosis." (PMID 37019475, 2023). "Our results demonstrate that ROs exhibit the most disturbed proteome due to PRPF8 mutation and suggest that changes in the expression of proteins associated with retinal degeneration could cause PRPF8 RP." (PMID 38605034, 2024). "The results illustrate InP/ZnS QDs‐caused retinal degeneration regulated by ferroptosis and mitophagy in RPE cells via inhibiting PRPF8‐related spliceosome." (PMID 39420512, 2024). "For example, why variants in the U5 snRNP genes PRPF6, PRPF8 and SNRNP200 are associated with retinal degeneration in adRP, while variants in the U5 snRNP genes EFTUD2 and TXNL4A are linked to craniofacial disorders, is not understood." (PMID 31304552, 2019). "Furthermore, the mutation of ubiquitously expressed and highly conserved splicing factors PRPF6, PRPF8, and PRPF31 causes retinal degeneration, suggesting a specialized role of the splicing machinery in the retina." (PMID 27151457, 2016).
breast carcinoma (7 papers, 2020 to 2025). "More recently, studies have shown that somatic mutations in PRPF8 are closely linked to various types of cancer, including breast cancer, liver cancer, colorectal cancer, and lung cancer." (PMID 40136404, 2025). "Knockdown of pan-cancer drivers PRPF8 caused cell apoptosis in breast cancer, which dedicated that PRPF8 is a proto-oncogene regulating cell viability." (PMID 32690086, 2020). "Moreover, in line with the robust inhibitory effects observed after silencing PRPF8, this core component of the major spliceosome has already been associated to malignancy in prostate cancer, hepatocarcinoma and breast cancer." (PMID 38049848, 2023). "Studies have also indicated that knockdown of PRPF8 in various types of breast cancer cells leads to increased intron retention, AS isoforms, and cell apoptosis, as well as affecting cellular protein metabolism, mitosis, and proteasome function." (PMID 40136404, 2025). "PRPF8 is overexpressed in breast cancer tissues and promotes cancer cell growth via the JAK-STAT signaling pathway and the inhibition of p21." (PMID 39795985, 2024). "The U4/U6-U5 tri-snRNP spliceosome complex and its core component PRPF8 are differently expressed between precancerous and breast cancer tissues." (PMID 39795985, 2024). "The splicing factor PRPF8 is critical for breast cell survival and has potential prognostic value in breast cancer." (PMID 36204322, 2022). "However, the function of PRPF8 is not entirely consistent across different breast cancer subtypes, demonstrating subtype specificity." (PMID 40136404, 2025).
ovarian carcinoma (6 papers, 2020 to 2025). A malignant neoplasm originating from the surface ovarian epithelium. "CircRNA-UBAP2 can promote the proliferation and restrain ovarian cancer apoptosis via regulating miR-382-5p and PRPF8." (PMID 34258298, 2021). "Meanwhile, circRNA-UBAP2 represses apoptosis and contributes to the proliferation of ovarian cancer by miR-382-5p/PRPF8 axis." (PMID 34122108, 2021). "CircRNA-UBAP2 can be used as a ceRNA of spongy miR-382-5p in ovarian cancer, increasing the expression level of PRPF8, promoting the proliferation of ovarian cancer cells, and inhibiting cell apoptosis." (PMID 34504842, 2021). "Our study indicated that circRNA-UBAP2 targeted miR-382-5p and downregulated its expression level, then the expression level of PRPF8 was increased, which relevant to progression of ovarian cancer." (PMID 32690086, 2020). "The mechanism that circRNA-UBAP2 promoted cell proliferation and inhibited cell apoptosis in ovarian cancer cells was regulated miR-382-5p/PRPF8 axis." (PMID 32690086, 2020). "In the present study, we conformed that circRNA-UBAP2 was upregulated in ovarian cancer tissues and cell lines, and circRNA-UBAP2 promoted cell proliferation and inhibited cell apoptosis of ovarian cancer through miR-382-5p/PRPF8 axis." (PMID 32690086, 2020). "Furthemore, circRNA-UBAP2/miR-382-5p/PRPF8 axis affected the proliferation, apoptosis and cell cycle of ovarian cancer through the mechanism of competing endogenous RNAs (ceRNA)." (PMID 32690086, 2020). "circRNA-UBAP2 acted as a ceRNA to sponged miR-382-5p, increased the expression level of PRPF8, and prompted proliferation and inhibited apoptosis in ovarian cancer cells." (PMID 32690086, 2020). "Furthermore, circRNA-UBAP2 acted as an oncogene in ovarian cancer, and circRNA-UBAP2 acted as a ceRNA to sponged miR-382-5p, increased the expression level of PRPF8, and prompted proliferation and inhibited apoptosis in ovarian cancer cells." (PMID 32690086, 2020). "Consequently, circRNA-UBAP2 upregulated expression level of PRPF8 by sponged miR-382-5p acted as a ceRNA, promoted proliferation and inhibited apoptosis in ovarian cancer cells." (PMID 32690086, 2020). "Additionally, RT-qPCR result showed that the expression of PRPF8 was higher in ovarian cancer tissues than that in adjacent tissues." (PMID 32690086, 2020). "Moreover, increased PRPF8 protein levels in ovarian cancer cells protect cells from apoptosis." (PMID 36560714, 2022). "In ovarian cancer, PRPF8 expression significantly promotes ovarian cancer cell proliferation and inhibits apoptosis through the circRNA-UBAP2/miR-382-5p/PRPF8 pathway." (PMID 40136404, 2025). "Furthermore, it has been identified that miR-382-5p can induces apoptosis by targeting PRPF8 and SPIN1 in ovarian cancer and lung cancer, respectively." (PMID 34122108, 2021). "Moreover, there was a negative correlation existed between expression level of PRPF8 and miR-382-5p in ovarian cancer tissues." (PMID 32690086, 2020). "However, there is no report about the miR-382-5p targeted PRPF8 and effect on ovarian cancer." (PMID 32690086, 2020).
retinal disease (6 papers, 2007 to 2025). "Most PRPF8 variants are primarily associated with retinal diseases; however, we analyze a family with multiple members diagnosed with NDDs." (PMID 40066647, 2025). "Additionally, the reasons why different PRPF8 mutations and/or varying expression levels contribute to distinct diseases, such as various cancers or retinal diseases, remain elusive." (PMID 40136404, 2025). "Collectively these elucidate the role of PRPF8/Brr2 regulatory mechanisms in splicing and the molecular basis of retinal disease, informing therapeutic approaches." (PMID 38605034, 2024). "Using our optimized system, we generated other isogenic models of inherited retinal diseases (IRDs), including the c.1481C>T (p.T494M) mutation in PRPF3 and the c.6926A>C (p.H2309P) mutation in PRPF8." (PMID 39795970, 2024). "To test the PE technology in hiPSCs with relevance to retinal disease, we chose three IRD genes with ubiquitous expression but associated with an isolated retinal phenotype NMNAT1, PRPF3, and PRPF8." (PMID 39795970, 2024).
hepatocellular carcinoma (4 papers, 2023 to 2026). A malignant tumor that arises from hepatocytes. "PRPF8 increases the aggressiveness of hepatocellular carcinoma by regulating the FAK/AKT pathway via fibronectin 1 splicing." (PMID 40136404, 2025). "Notably, NCBP1, PRPF8, and SNRPD1 were dependent genes in both CRC and hepatocellular carcinoma." (PMID 41195591, 2026).